LIN9 (lin-9 DREAM MuvB core complex component)
Description:
Acts as a tumor suppressor. Inhibits DNA synthesis. Its ability to inhibit oncogenic transformation is mediated through its association with RB1. Plays a role in the expression of genes required for the G1/S transition.
Synonyms: BARA; TGS; BARPsv; Lin-9; TGS2
Tractability: PROTAC: UniProt records ubiquitination sites on it; ubiquitination databases record sites on it.
Gene: Protein-coding gene on chromosome 1 (226,231,149 to 226,309,869, reverse strand). Ensembl gene ENSG00000183814.
Subcellular location: Nucleus, nucleoplasm
Subcellular location (Human Protein Atlas): Nucleoplasm
Pathways (Reactome):
Cell Cycle: Cyclin A:Cdk2-associated events at S phase entry; Cyclin E associated events during G1/S transition; G0 and Early G1; G1/S-Specific Transcription; Polo-like kinase mediated events; Transcription of E2F targets under negative control by DREAM complex; Transcription of E2F targets under negative control by p107 (RBL1) and p130 (RBL2) in complex with HDAC1
Gene Ontology:
Molecular function: protein binding; DNA binding
Biological process: negative regulation of DNA-templated transcription; positive regulation of transcription by RNA polymerase II; regulation of cell cycle; regulation of DNA-templated transcription; regulation of transcription by RNA polymerase II; DNA-templated transcription
Cellular component: nucleoplasm; DRM complex; nucleus; RNA polymerase II transcription regulator complex; transcription repressor complex
Genetic constraint (gnomAD): Loss-of-function variants: 2 observed, 32.09 expected, observed/expected ratio (o/e) 0.0623, 90% interval 0.024 to 0.2. The upper end of that interval is the gene's LOEUF score, 0.2, which puts it in group 1 of 6, group 1 being the genes least tolerant of losing a copy. Missense variants: 209 observed, 308.39 expected, observed/expected ratio (o/e) 0.68, 90% interval 0.61 to 0.76. Synonymous variants: 89 observed, 105.14 expected, observed/expected ratio (o/e) 0.85, 90% interval 0.71 to 1.01.
Homologues: Orthologues: macaque LIN9 (99% identical), dog LIN9 (99% identical), guinea pig LIN9 (98% identical), pig LIN9 (97% identical), rat Lin9 (97% identical), mouse Lin9 (97% identical), chimpanzee LIN9 (93% identical), rabbit LIN9 (90% identical), tropical clawed frog lin9 (86% identical), zebrafish lin9 (78% identical), Drosophila melanogaster mip130 (39% identical), Caenorhabditis elegans lin-9 (33% identical), and 1 more.
Diseases named in the same sentence as LIN9 in open-access papers:
LIN9 is named in the same sentence as 21 diseases in open-access papers, as found by Europe PMC text mining. Sharing a sentence is not in itself a finding about the gene and the disease. The quoted sentences say what the papers report.
breast carcinoma (4 papers, 2015 to 2021). "Analysis of possible targets for miR-29b-1-5p reveals that the top 4 targets, USP28, NEUROD1, LIN9 and WDR26 have all been previously associated with breast cancer." (PMID 30323900, 2018). "In contrast little is known about the expression of other core complex components in cancers although LIN9 is part of the Mammaprint breast cancer profile which is prognostic for metastatic disease." (PMID 25889361, 2015).
triple-negative breast carcinoma (4 papers, 2019 to 2022). An invasive breast carcinoma which is negative for expression of estrogen receptor (ER), progesterone receptor (PR), and human epidermal growth factor receptor 2 (HER2). "Another gene of interest, LIN9, is highly expressed in triple negative breast cancer and is associated with poor outcomes in this disease." (PMID 33747961, 2021). "For example, in the treatment of triple-negative breast cancer, paclitaxel resistance can be reversed by decreasing LIN9 expression, thus suggesting that paclitaxel resistance in triple-negative breast cancer can be reversed by combining bromo- and extra-terminal domain inhibitors with paclitaxel." (PMID 35699421, 2022). "However, some target genes of BETi, such as LIN9 gene in triple-negative breast cancer, do not possess any corresponding SEs sites." (PMID 31105558, 2019).
embryonal carcinoma (2 papers, 2011 to 2013). A non-seminomatous malignant germ cell tumor characterized by the presence of large germ cells with abundant cytoplasm resembling epithelial cells, geographic necrosis, high mitotic activity, and pseudoglandular and pseudopapillary structures formation. "Consistent with the recent description of a DREAM-like complex in embryonal carcinoma F9 cells, we find that LIN9 associates with the other core-subunits of DREAM and with B-MYB, but not with pocket proteins or E2F4 in ESCs." (PMID 23667535, 2013). "In mouse embryonal carcinoma cells knock-down of lin-9 or lin-54 resulted in significant cell cycle defects, while knock down of lin-37 or lin-52 had no such effects." (PMID 21570388, 2011).
ovarian carcinoma (2 papers, 2021 to 2023). A malignant neoplasm originating from the surface ovarian epithelium.
glioma (1 paper, 2023). A benign or malignant brain and spinal cord tumor that arises from glial cells (astrocytes, oligodendrocytes, ependymal cells). "Overall, the expression of LIN9, MCM8, CEP72, POLA1, DBF4, NDE1 and CDKN2C increase the prognostic risk for patients with glioma." (PMID 37349788, 2023). "The correlation between E2F4 and LIN9, MCM8, CEP72, POLA1, DBF4, NDE1 or CDKN2C expression in glioma tissues was analyzed using CGGA." (PMID 37349788, 2023).
tumor (12 papers, 2009 to 2025). "Tumour growth inhibition by hTRM9L is linked to increased transcription of the RB interacting protein LIN9 and to a failure of hTRM9L-expressing cells to mount a hypoxic response." (PMID 23381944, 2013). "For example, Lin9 is a tumor suppressor that inhibits DNA synthesis and acts synergistically with the well-knownRb1 gene to prevent rapid, uncontrolled cell division." (PMID 33419422, 2021). "Studies in cell lines and mouse genetic models reveal the importance of another MuvB subunit, LIN9, for both cell proliferation and tumor suppression, emphasizing its structural role in both DREAM and MMB." (PMID 29942794, 2018). "We inoculated the parental and LIN9 knockdown cells and analysed for tumour formation on the CAM at 7 days." (PMID 23381944, 2013). "One possible explanation is that hTRM9L-dependent induction of LIN9, in addition to inhibiting exit from G1, short circuits the response to hypoxia and prevents cells from thriving in the oxygen poor tumour microenvironment." (PMID 23381944, 2013). "Our study links hTRM9L and tRNA modifications to inhibition of tumour growth via LIN9 and HIF1-α-dependent mechanisms." (PMID 23381944, 2013). "Our experiment results associated with LIN9 loss of function in hTRM9L expressing SW620 cells, clearly demonstrate that part of the mechanism of tumour growth inhibition involves a known component of the DREAM complex and cell cycle machinery." (PMID 23381944, 2013). "LIN9 is involved in progression through the cell cycle and is a tumor suppressor that inhibits DNA synthesis, thus having significant cancerous potential." (PMID 19208118, 2009). "LIN9 has been demonstrated to act as a tumour suppressor itself as it can bind to pRB." (PMID 23381944, 2013). "The prioritization of the hub genes in the gene expression profiles suggestive of tumor immune evasion and immunotherapy response occurs in the order of RAB31 > TNPO2 > OBSCN > IRAK3 > LIN9 > SEC16B." (PMID 34359748, 2021). "There are a further eight tumor-suppressor genes (DLEU2, CDKN2C, SPRY4, UBE2QL1, LIN9, TFPI2, LRIG3, DUSP1) and six genes serve as both oncogenes and tumor-suppressor genes (FOXO1, CAV1, KLF6, CDK6, PLK1, CTGF)." (PMID 30563222, 2018). "The synMuv B genes encode homologues of the dREAM complex, which are conserved across animals and plants, including the LIN-35/retinoblastoma (Rb) tumor suppressor, and the Rb complex components LIN-53 /RbAp48, LIN-37/MIP40, LIN-54/MIP120, DPL-1 /DP, LIN-9/MIP130." (PMID 39879188, 2025). "Notably, RAB31, IRAK3, OBSCN, LIN9, TNPO2, and SEC16B expressions were inversely correlated with the gene expression profiles suggestive of tumor purity of the hub cancer." (PMID 34359748, 2021). "However, the negative association between the levels of LIN9 and SEC16B and the gene expression profile suggestive of CAFs infiltrations of the hub cancers suggested that the hub genes are likely to be involved in the regulation of tumor immune evasion via different mechanisms." (PMID 34359748, 2021).
cancer (8 papers, 2015 to 2022). A tumor composed of atypical neoplastic, often pleomorphic cells that invade other tissues. "None of the signature genes except TERT was cataloged by the expert-curated Cancer Gene Census44 (as of July 2020), although LIN9 and HELLS were recently implicated in cancer." (PMID 33420056, 2021). "Therefore, loss of function in Lin9 can lead to cancer-like growth of mutant cells that would eventually dominate the culture population." (PMID 33419422, 2021). "TNP02 and OBSCN expressions were weakly correlated, while LIN9 expression correlates negatively with the gene expression profiles suggestive of CAF infiltration in the hub cancers." (PMID 34359748, 2021). "Similarly, the expression levels of RAB31, IRAK3, and SEC16B were inversely correlated, while TNPO2 and LIN9 were positively correlated with gene expression profiles suggestive of MDSCs infiltration in the six cancer types." (PMID 34359748, 2021). "Similarly, we queried the survival differences between the mRNA expression levels of each hub gene across the combined cohorts of the hub cancers and found that higher mRNA expression levels of RAB31, IRAK3, SEC16B, and LIN9 predicted shorter survival durations of the hub cancer cohorts." (PMID 34359748, 2021). "The expression levels of MYBL2, RBL1, LIN9, and E2F5 in various cancers were significantly upregulated." (PMID 35664326, 2022). "Specifically, single nucleotide variation (SNV) of OBSCN is the most frequently predicted gene alteration, while SNV of SEC16B, IRAK3, TNPO2, LIN9, and RAB31 constituted 9%, 5%, 5%, 4%, and 2% of genetic alterations in the TCGA cohort of the hub cancers." (PMID 34359748, 2021). "By ChIP-seq, YAP does not colocalize with LIN9 to the promoters of cell cycle genes but instead binds to enhancers, consistent with recent data from human cancer cell lines where YAP also predominantly binds to distant sites." (PMID 32469866, 2020).
infection (6 papers, 2006 to 2023). The state of being infected such as from the introduction of a foreign agent such as serum, vaccine, antigenic substance or organism. "In this work, susceptible plants showed delayed expressions of Sl-SUS1, Sl-SUS3, Sl-LIN8 and Sl-LIN9 along with the continuous repression of several Sl-SUS4 to Sl-SUS7 isoforms throughout the course of infection." (PMID 32853354, 2021).
LIN9 also shares sentences with these, for which no sentence is quoted: urinary tract infection (2 papers); colorectal cancer (1); COVID-19 (1); cystitis (1); E. coli (1); lung carcinoma (1); male infertility (1); meningitis (1); metastatic disease (1); neuroblastoma (1); prostate carcinoma (1); Salmonella Infections (1); Stomach Cancers (1).